SRC (SRC proto-oncogene, non-receptor tyrosine kinase)
Diseases named in the same sentence as SRC in open-access papers (continued):
Sharing a sentence is not in itself a finding about the gene and the disease.
melanoma (continued). "Specifically, it was shown by kinase activity profiling that SRC is activated in primary human melanoma and its inhibition leads to reduced growth." (PMID 20663135, 2010). "Consistent STAT3 activation in melanoma results from SRC and JAK activation." (PMID 36852795, 2023). "A recent report showed a link between cofilin phosphorylation and SRC/AKT/mTOR pathway in melanoma." (PMID 35882839, 2022). "In addition to their roles in sensitizing melanoma cells to BRAFi, the SRC inhibitors Bos and Das, even at low doses (1 μM), prevented the invasive capacity of wild‐type AhR melanoma cells (red) in three‐dimensional spheroid assays." (PMID 36305167, 2022). "We performed co‐immunoprecipitation experiments to determine whether AhR and SRC are present in the same protein complex in melanoma cells (SKMel28)." (PMID 36305167, 2022). "Here, using a BRAFi‐resistant PDX melanoma model, we demonstrated that SRC inhibition (dasatinib) significantly controlled tumor growth and remarkably re‐sensitize melanoma cells to BRAFi (dabrafenib), doubling the overall survival rate compared to BRAFi alone." (PMID 36305167, 2022). "Similarly, SRC inhibition also selectively sensitized de-differentiated melanomas to BRAF inhibition." (PMID 36271142, 2022). "In addition, we show in melanoma cells that canonical activation of AhR mediates the activation of the SRC pathway and promotes the acquisition of an invasive and aggressive resistant phenotype to front‐line BRAFi treatment in melanoma." (PMID 36305167, 2022). "Indeed, we showed that activation of SRC leads to the reactivation of the EGFR after its phosphorylation (Y845) in BRAFi‐resistant melanoma cell lines (Fig EV5A–C)." (PMID 36305167, 2022). "In this respect, SRC inhibitors have been tested in melanoma." (PMID 36305167, 2022). "Interestingly, knockdown expression revealed that melanoma cells sensitive to the compound are “addicted” to SRC and LYN activity." (PMID 31040916, 2019). "Targeting SRC in melanoma has been of interest for over a decade." (PMID 31040916, 2019). "Shp2 cooperates with c-SRC inmodulation of Stat3 phosphorylation in melanoma cells." (PMID 28085101, 2017). "Interestingly, the expression of SRC gene had undergone down- and up-regulation, respectively, when Mel-2 and Mel-3 melanoma cells were treated with 5AzaCdR combined with TSA." (PMID 22984562, 2012). "Our hypothesis is also further reinforced by published reports in BRAFV600E melanoma that showed activation of the SRC pathway by Aryl hydrocarbon Receptor (AhR) promotes the acquisition of an invasive and aggressive phenotype resistant to front-line BRAF inhibitors." (PMID 40481178, 2025). "Moreover, SRC activates N-cadherin phosphorylation, disrupting the β-catenin-cadherin binding and promoting β-catenin accumulation in the cytoplasm and nucleus during melanoma cell transendothelial migration." (PMID 40399946, 2025). "This gives some hints of how SRC may participate in melanoma cell reprogramming." (PMID 36305167, 2022). "SRC and FAK also regulate key intracellular signaling pathways that support melanoma cell survival, proliferation and migration." (PMID 40563555, 2025). "Treatment of A375 melanoma cells with 3, 5 DCPBC for 4 and 18 h profoundly suppressed phosphorylation of critical targets like EGFR, SRC, STAT3, JNK1/2, and MSK." (PMID 35208960, 2022). "Combinations of SRC and MEK inhibitors have shown benefit in preclinical studies across several tumour types including ovarian, melanoma, non‐small‐cell lung carcinoma, breast and other solid tumours." (PMID 34856074, 2022). "It was also demonstrated that SRC small molecule inhibitor overcame the MAPKi and PI3K/mTORi dual-drug resistance in melanoma." (PMID 35965583, 2022). "It has been shown that NEDD9 acted through SRC and STAT3 to promote invasion in melanoma, cervical cancer, and ovarian cancer." (PMID 34314382, 2021).
melanoma (continued). "WB analyses revealed a marked increase of the phospho-active forms of FAK1 (pFAK-Y397 and -Y576) and SRC (pSRC-Y416) in BPA−/− tumors and in human melanoma cells silenced for AMBRA1, as well as in iLN metastasis of BPA−/− and in melanocytic nevi of BA−/− mice." (PMID 33953176, 2021). "In melanoma cells, STAT5 acts to mediate resistance to apoptosis and is reported to be activated by both JAK2 and SRC kinases." (PMID 28223541, 2017). "Our results agree with previous observations of the presence of constitutive activation of SRC and STAT1, 3, and 5 proteins in melanoma tumors." (PMID 28223541, 2017). "After VE-cadherin silencing, phosphorylation of SRC, ERK and JNK was significantly decreased in both cell lines, and that of AKT in BLM melanoma cells." (PMID 27966446, 2017). "Endocrine or paracrine as well as autocrine GH binds to abundantly expressed GHR on human melanoma and activates the JAK2 as well as SRC kinases." (PMID 28223541, 2017). "VE-cadherin-mediated integrin signaling occurred through specific activation of SRC, ERK and JNK, including AKT in melanoma." (PMID 27966446, 2017). "We found that c-CBL knockdown resulted in reduced FAK, SRC and GRB2 protein expression in several melanoma cell lines." (PMID 27472394, 2016). "Our data demonstrate that the effects of c-CBL knockdown in melanoma, were accompanied by decreases in the protein and mRNA levels of FAK, SRC and GRB2, suggesting the involvement of the FAK-GRB2-SRC nexus in the consequences of c-CBL alteration." (PMID 27472394, 2016). "SRC protein was readily detectable in multiple melanoma cell lines and NIK was overexpressed in melanoma cell lines but was detected at low levels in normal melanocytes." (PMID 22948084, 2012). "miR-31 targets include oncogenic kinases such as SRC, MET, NIK (MAP3K14) and the melanoma specific oncogene RAB27a." (PMID 22948084, 2012). "We nominated SRC, MET, NIK and RAB27a as possible miR-31 targets in melanoma; these genes are known to play pro-tumorigenic roles in melanoma." (PMID 22948084, 2012). "From the SRC kinases only FYN was higher expressed in the tumors compared to the benign precursor lesion, consistent with its more prominent role in xmrk-driven melanoma." (PMID 22693581, 2012). "It has been demonstrated that luteolin exerts antimelanoma effects in vitro and in vivo without overt toxicity to normal cells and also in melanoma-bearing mice through the suppression of STAT3 signaling via binding to SRC protein." (PMID 39234106, 2024). "Signaling pathway proteins affected by EcTI contribute to the development of cancer and metastases, such as SRC, that promote metastasis in melanoma, FAK/SRC, whose interactions increase cell-to-cell adhesion with a consequent collective increase in cell migration and PI3K protein expression." (PMID 35566311, 2022). "The efficient combined targeting of EGFR, SRC, STAT, and MAPK by 3, 3′- (3, 5-DCPBC) in melanoma cells may long term assist clinicians to prevent melanoma growth and even to overcome drug resistance." (PMID 35208960, 2022). "The direct role of AhR in regulating the phosphorylation of SRC (Y416) and EGFR (Y845) may promote together the acquisition of the aggressive/invasive EMT like phenotype of BRAFi‐resistant melanoma (Synopsis)." (PMID 36305167, 2022). "Together these results identify the central role of the AhR/SRC axis in supporting nongenetic cell reprogramming of melanoma cells exposed to targeted therapy." (PMID 36305167, 2022). "Finally, recent data on the prime role of the tyrosine kinases SRC and the AKT/mTOR axis in melanoma progression highlights the unique implication of 3, 3′- (3, 5-DCPBC) as a promising small molecule drug candidate." (PMID 35208960, 2022). "One possible mechanism may be the suppression of the de-differentiated state, as SRC and RAC1 maintained markers of de-differentiation in human melanoma cells." (PMID 36271142, 2022).
melanoma (continued). "Therefore, our results implicate the JAK2-STAT5 as well as the SRC pathway as the principal molecular mediators of GH-mediated upregulation of MITF expression and activity in melanoma." (PMID 31547367, 2019). "We performed several experiments to test the role of each of these mechanisms in melanoma cells and found that none was sufficient to explain how SRC was regulating LATS in these cells." (PMID 30559289, 2019). "We additionally found other routes of GH induced signaling downstream of JAK2 and SRC, including GH-induced increases in phosphorylation states of STAT5, STAT1, STAT3 as well as of AKT, mTOR, and ERK1/2 in all four human melanoma cell lines." (PMID 28223541, 2017). "We and others have shown that levels of SRC expression or phosphorylation do not predict sensitivity to dasatinib in melanoma cell lines." (PMID 25594008, 2014). "Although levels of SRC expression are not predictive of response to dasatinib in vitro, SRC is expressed in all melanoma cell lines tested and phosphorylation of SRC is inhibited by dasatinib." (PMID 25594008, 2014). "Co-expression of SRC, ANXA1, CAV-1 and EphA2 was detected in 35/113 (31 %) of melanoma samples." (PMID 25594008, 2014). "Although miR-31 has been shown to act as either an oncomiR or tumor suppressor in various tumor types, in this study we clearly establish miR-31 as a tumor suppressor, demonstrate that it targets multiple oncogenes such as SRC, MET, NIK and RAB27a and regulates the expression of EZH2 in melanoma." (PMID 22948084, 2012). "Although the effect of SRC kinases on gene expression has not yet been investigated in human melanoma, accumulating data indicate that this pathway plays a vital role for the malignant cells." (PMID 20663135, 2010). "A phosphoproteomic analysis of melanoma tumor cells and cell lines showed that metastatic cells expressed larger amounts of CDCP1 and that the forced expression of CDCP1 in melanoma cell lines led to the activation of SRC and to an increase in metastatic potential." (PMID 25876044, 2015). "Dasatinib, an SRC inhibitor, was shown previously to exhibit a higher activity towards YES rather than SRC, and could be a promising treatment for LKB1-mutated melanoma." (PMID 24743024, 2014). "However, in melanoma cell lines regardless of their sensitivity to dasatinib, extended exposure to dasatinib inhibited phosphorylation of SRC in all melanoma cell lines tested." (PMID 25594008, 2014). "Thus, inhibition of SRC alone does not predict sensitivity to inhibition of proliferation by dasatinib in melanoma cells." (PMID 25594008, 2014). "However, the relation between AhR and SRC has not yet been explored in melanoma." (PMID 36305167, 2022). "Moreover, melanoma cells made resistant to the BRAF inhibitor vemurafinib, which acts upstream of MEK activation and signalling, exhibited activated SRC signalling in vitro and in vivo, and exhibited sensitivity to SRC inhibition by both dasatinib and saracatinib." (PMID 29435137, 2018). "Thus, our results indicating significant basal activation of JAK2, SRC, STATs 1, 3, and 5, in melanoma aids in resolving finer aspects of STAT1 vs. STAT3 as well as acts as a springboard for dissecting studies on cytokine-induced STAT mediated cross-talks between JAK and SRC pathways." (PMID 28223541, 2017). "The synergistic impact on cell viability with the addition of a SRC inhibitor to BRAF + EGFR targeting was conserved across BRAFV600E CRC cell lines, but not BRAFV600E melanoma cells." (PMID 36759733, 2023). "Vemurafenib, an inhibitor of mutant BRAF used for the treatment of melanoma, also inhibits PTK6, but not SRC, at nanomolar concentrations." (PMID 36228719, 2022). "The results show that SRC depletion in YUSIV, YUSIK and YUGASP melanoma cells induced growth arrest whereas 501 mel cells were not affected." (PMID 31040916, 2019).
melanoma (continued). "Human melanoma cells MDA-MB-435 were incubated for 6 h with inhibitors of JAK2, STAT5, SRC, or ERK1/2 (p44/42-MAPK) at concentrations where they do not reduce cell viability by more than 20% in 24 h." (PMID 31547367, 2019). "Basal level phosphorylation of GH-regulated intracellular signaling networks like JAK2, STATs 1, 3, 5, ERK1/2, SRC, AKT and mTOR in absence of externally added GH suggested the presence of an autocrine ligand-receptor loop existent and critical in these four melanoma cell lines." (PMID 28223541, 2017).
colon carcinoma (71 papers, 2002 to 2025). "There is evidence suggesting that different colon polyps, with or without malignant potential, exhibit similar gene expression changes in the WASL- and SRC-encoding genes, as observed in our colon cancer-related analyses." (PMID 39234565, 2024). "We detected four colorectal-cancer-related mutations on the root branch, including SRC, which has been shown to play an important role in the development or progression of human colon cancer and was recently postulated to be associated with liver metastasis." (PMID 38685065, 2024). "Intriguingly, our study indicated that high expression of SRC and SRC_pY527 was associated with superior prognosis in colon cancer patients." (PMID 33758598, 2021). "Our results revealed that loss of PTPRO promotes resistance to EGFR inhibitors in colon cancer cells by maintaining activated SRC and EGFR/MAPK pathway." (PMID 25301722, 2014). "Elevated SRC activity is associated with invasiveness in colon tumors, suggesting that SRC induces cellular changes that promote tumor progression." (PMID 21049007, 2010). "And mutations of SRC can be involved in the malignant progression of colon cancer." (PMID 33376727, 2020). "Eighty percent of patients with colon cancer overexpress SRC in tumor tissue but SRC therapy may causes weaken immune responses." (PMID 30949321, 2019). "Importantly, hyperactivation of SRC/EGFR signaling triggered by loss of PTPRO leads to high resistance of colon cancer to EGFR inhibitors." (PMID 25301722, 2014). "Studies have revealed that SRC activity in CRC tissues is 5- to 8-fold higher than in normal colonic mucosa, while primary colon tumors show 5- to 7-fold increased SRC activity relative to adjacent normal tissue." (PMID 40559953, 2025). "Overexpression of SRC is involved with colon cancer and often results in metastasis via its signalling pathways." (PMID 36809921, 2023). "Pancreatic, ovarian, and colon cancers have been associated with VEGF, EGFR, SRC, and JAK overexpression and STAT3 activation." (PMID 36852795, 2023). "High expression of EGFR or IGFBP2 was associated with poor prognosis while high expression of SRC or SRC_pY527 predicted superior survival in colon cancer." (PMID 33758598, 2021). "In this study, we established a novel proteomic signature (including EGFR, IGFBP2, SRC and SRC_pY527) for prognostic prediction of colon cancer using TCPA database." (PMID 33758598, 2021). "Further precise regulation mechanisms of SRC and SRC_pY527 in colon cancer are needed to be explored." (PMID 33758598, 2021). "Studies have reported that FA inhibits endothelial cell proliferation through activating the FRα, and inhibits colon cancer cell proliferation through activating the FRα/c-SRC pathway." (PMID 29070520, 2017). "Oxaliplatin was found to activate SRC in colon cancer cells by ROS-dependent pathway, which leads to the activation of EGFR signaling and decreasing of the effects of cetuximab." (PMID 28288572, 2017). "SRC activity is correlated with colon cancer disease stage, and cell lines with elevated SRC activity are more motile and invasive in vitro." (PMID 25860875, 2015). "Here we found that up-regulation of SRC activity by loss of PTPRO dramatically affects activation of EGFR/MAPK pathway, further confirming the contribution of the SRC kinase to colon cancer development and progression." (PMID 25301722, 2014). "This analysis revealed that the expression levels of WASL, GRB2, SRC, and Tks4 were the most important variables among the entire gene set; therefore, we conclude that the examination of these four genes should be sufficient for colon cancer diagnosis." (PMID 39234565, 2024).
colon carcinoma (continued). "Given the pivotal roles of SRC and EGFR as oncogenes impacting colon cancer development, exploring Tks4’s role in colon cancer becomes imperative for a comprehensive understanding of the pathomechanisms underlying colon cancer formation." (PMID 39234565, 2024). "In addition, BCKDK promoted tumor growth and metastasis by interacting with SRC or mTOR in colon cancer or hepatic carcinoma." (PMID 35498541, 2022). "In colon cancer, exosomes have been found to transfer mutant oncogenes such as KRAS and SRC to other colon cancer cells lacking these mutations to further promote tumor invasion." (PMID 36139610, 2022). "It should be noted that the strong immune system is needed to suppress the cancer cells and suppression of the SRC gene as well as having a strong immune system could be effective in treating colon cancer." (PMID 30949321, 2019). "Oncogenes including AKT1, JUN, SRC are a gene set that are also prominent in colon cancer." (PMID 30774816, 2018). "Recently, it was shown that CAFs led migration of colon cancer cells via surface associated FGF-2, which binds to the FGFR located on the surface of cancer cells, activating SRC and inducing integrin αvβ5 expression which leads to adhesion of colon cancer cells to fibroblasts." (PMID 27929432, 2016). "Indeed, we previously showed that LOX signals through SRC to increase colon cancer tumor cell proliferation, invasion and metastasis." (PMID 26077591, 2015). "Short hairpin RNA-mediated suppression of PTPα, for instance, reduced SRC activity by up to four-fold in human breast and colon cancer cell lines, while overexpression of PTP1B increased SRC activity and promoted anchorage-dependent growth of colon cancer cells." (PMID 26087188, 2015). "Hence, increased SRC activity represents an independent indicator of poor clinical prognosis in all stages of colon cancer." (PMID 23900414, 2013). "Additionally, we further confirmed that the interaction between MET and SRC and the formation of MET/SRC/EGFR complex contributed to constitutive MET activation, providing a rationale for combinatorial inhibition of EGFR and MET or EGFR and SRC in therapy targeting colon cancer." (PMID 24714091, 2014). "In addition, the Apc-Cdkn1a network also suggests that certain interactions previously associated with other cancer models – such as the SRC-CCND1 functional association found in prostate cancer, or the phosphorylation of CDK4 by SRC in a cell line – are relevant in this model of colon cancer." (PMID 20824133, 2010). "We entered the analyzed colon cancer marker gene set (CD2AP, GRB2, WASL, SRC, CTTN, CAPZA1, and Tks4) into this tool to elucidate which cancer hallmark-related pathways are influenced by these proteins." (PMID 39234565, 2024). "The expression levels of CD2AP, GRB2, WASL, and CAPZA1 are generally downregulated, while those of SRC and CTTN are upregulated in colon cancer samples compared with their levels in normal samples at the RNA and/or protein levels." (PMID 39234565, 2024). "There is accumulating evidence that the biological synergy between SRC and EGFR promotes colon cancer tumorigenesis." (PMID 25301722, 2014). "In addition, ICAM1 neutralizing antibodies have also been found to inhibit SRC and STAT3 pathways and inhibit colon tumor metastasis and angiogenesis." (PMID 39971940, 2025).